YTHDF1 (YTH N6-methyladenosine RNA binding protein F1)
Diseases named in the same sentence as YTHDF1 in open-access papers (continued):
Sharing a sentence is not in itself a finding about the gene and the disease.
tumor (continued). "Prior injection of YTN16 cells with sgYTHDF1-1 was able to confer the host antitumor ability to reject the subsequent implantation of tumor cells with normal YTHDF1 expression." (PMID 35193930, 2022). "As an independent prognostic factor, c-Myc knockout can inhibit the expression of YTHDF1, thereby inhibiting the proliferation and chemoresistance of tumor cells." (PMID 35022030, 2022). "YTHDF1 contributes to the tumorigenic behavior of cancer cells and facilitates a favorable tumor microenvironment." (PMID 35884552, 2022). "Eventually, the relation between YTHDF1 and tumor cell immune infiltration, glycolysis, ferroptosis, and the ceRNA network was surveyed, to provide a basis for the development of new treatment strategies for ESCA." (PMID 35401696, 2022). "Extending from the results above, we evaluated the miR-16-5p-mediated YTHDF1 inhibition and its anti-tumor effect in vivo using similar set-ups." (PMID 35319018, 2022). "Our study reveals that METTL3-FRAS1 plays a crucial role in NSCLC cell proliferation, colony formation, and tumor growth through the regulation of CDON by cooperating YTHDF1." (PMID 36008805, 2022). "The results showed that depletion of YTHDF1 inhibited tumor proliferation, migration, and invasion, which was partially abolished by overexpression of FOXM1." (PMID 35197112, 2022). "In lung adenocarcinoma, the Wnt/β-catenin signaling can inhibit FTO expression, under the effect combined with YTHDF1, the increasing m6A level of c-Myc can promote tumor glycolysis and tumorigenesis." (PMID 35022030, 2022). "Western blot analysis on the extracted tumor tissues showed similar results with the in vitro tests that the depletion of YTHDF1 inhibited PKM2 expression in xenograft tumors in mice." (PMID 35319018, 2022). "Compared with wild-type mice, YTHDF1-deficient mice contained higher levels of CD8+ cytotoxic T cells, and natural killer (NK) cells in tumor immune infiltration." (PMID 35590394, 2022). "For example, METTL3 can regulate the dynamic balance and differentiation of T cells, and YTHDF1 can regulate the number of CD8+ T cells infiltrated in tumor microenvironment in mice." (PMID 35590394, 2022). "YTHDF1-mediated glutamine metabolism via GLS1 has been shown to promote cisplatin chemoresistance in CRC cells, while the combination of YTHDF1 silencing and cisplatin leads to synergistic effect in suppressing tumor growth." (PMID 35884552, 2022). "YTHDF1 is involved in almost the whole process of tumor biological behavior, and plays an important role in regulating transcription, translation, protein synthesis, angiogenesis, and EMT." (PMID 36035182, 2022). "The excessive tumor growth induced by METTL3 upregulation was blocked by FRAS1 or YTHDF1 knockdown, including tumor volume and tumor weight." (PMID 36008805, 2022). "In turn, tumor hypoxia regulated the function of m6A reader YTHDF1 to drive the malignancy of hepatocellular carcinoma." (PMID 36105819, 2022). "It is reported that YTHDF1 functions as a tumor promoter in various cancers such as gastric cancer, HCC, NSCLC." (PMID 36008805, 2022). "Knocking down YTHDF1 in DC cells can enhance the cross presentation of tumor antigen and the cross start of CD8+T cells." (PMID 36561529, 2022). "YTHDF1 functions as a tumor suppressor of ocular melanoma by recognizing m6A-modified RNA and accelerating the translation of histidine trinucleotide binding protein 2 (HINT2)." (PMID 36017491, 2022). "Altogether, these findings imply that YTHDF1 confers an immunosuppressive tumor microenvironment in CRC patients." (PMID 35884552, 2022). "Inhibiting YTHDF1 via gene knockdown or miR-16-5p would significantly abolish YTHDF1-dependent tumor growth and metastasis." (PMID 35319018, 2022). "Tumor tissue staining of YTHDF1 and HNRNPA2B1 showed moderate staining in the nucleus, and negative staining was observed in the normal tissues." (PMID 35372339, 2022).
tumor (continued). "Flow cytometry revealed that the proportion of the infiltrating immune cells (CD45+ cells) in the tumor was significantly higher in YTHDF1 knockout group than that in the control group (p<0.05)." (PMID 35193930, 2022). "In contrast, YTHDF1 stimulates the translation of the tumor suppressor Hint2 in melanoma, thereby inhibiting tumor progression." (PMID 36360287, 2022). "GSEA confirmed that low YTHDF1 or YTHDF2 tumor expression reflects the gene set of immune hot tumors." (PMID 36479088, 2022). "Except for ZC3H13, the other three genes (CBLL1, ELAVL1 and YTHDF1) were positively correlated with purity state of tumor cell in LUSC." (PMID 36261786, 2022). "YTHDF1 has been shown to be involved in tumour cells immune evasion, while YTHDF2 promotes tumour cell proliferation." (PMID 36422864, 2022). "Apart from its tumor cell intrinsic role, we demonstrated that YTHDF1 expression in GC can suppress antitumor immunity by preventing the recruitment of mature DCs in tumors, thereby suppressing adaptive immunity." (PMID 35193930, 2022). "YTHDF1 is a typical and highly expressed m6A reader protein in BC tissues and cell lines, and its high expression status is thought to be indicative of tumor size, metastasis, poor prognosis, and chemotherapy resistance." (PMID 36035182, 2022). "YTHDF1 was differentially expressed in more than half the cancers when comparing tumours to adjacent normal tissue." (PMID 35075167, 2022). "Deletion of m6A binding protein YTHDF1 in mouse show an elevated antigen-specific CD8 T cell anti-tumor response." (PMID 36092891, 2022). "Mechanistically, YTHDF1 recognized m6A in several lysosomal cathepsin mRNA transcripts, boosting their translation, enhancing tumour antigen degradation and reducing cross‐presentation." (PMID 35220694, 2022). "Consistently, the cases with YTHDF1-high expression displayed poor survival and tumor recurrence as compared with those with low expression in GEO database." (PMID 33791305, 2021). "Next, we explored YTHDF1 coexpression networks using the LinkedOmics database to verify the potential function of YTHDF1 in tumor tissue, and used BLCA as an example to illustrate the potential effect." (PMID 34026603, 2021). "The binding between m6A-marked mRNAs and YTHDF1 then boosts lysosomal protease translation, which suppresses the cross-presentation of engulfed tumor neoantigens." (PMID 34630412, 2021). "YTH N6-methyladenosine RNA binding protein 1 (YTHDF1) has been indicated proven to participate in the cross-presentation of tumor antigens in dendritic cells and the cross-priming of CD8+ T cells." (PMID 34026603, 2021). "HeLa cells with YTHDF1 knockdown and control group were injected subcutaneously into nude mice, and tumor growth was monitored." (PMID 33816306, 2021). "By recognizing and binding their target mRNAs, YTHDF1 enhances antigen degradation in DCs, which limits DCs to present tumor neoantigens to T cells." (PMID 34103054, 2021). "Our findings illustrated that ALKBH5 and YTHDF1 have potential in tumor immunity and provided novel insights into the relationship between m6A modification and immunity." (PMID 34079761, 2021). "Similar results in Han D’s study exhibited a deficiency of YTHDF1 that promoted the antigen-specific activation of CD8+ T cells and attributed to the enhanced capability of DCs to present tumor neoantigens." (PMID 34332578, 2021). "In order to investigate the role of YTHDF1 in tumorigenesis in vivo, we conducted subcutaneous tumor formation experiments in nude mice." (PMID 33816306, 2021). "Inhibiting the expression of YTHDF1 in classical dendritic cells can enhance the cross-presentation of tumor antigens and the cross-activation of CD8+ T cells in vivo." (PMID 35095993, 2021). "Deficiency of YTHDF1 functionally prevents NSCLC cell proliferation and tumor formation through inhibiting the translational efficiency of cyclin-dependent kinase 2 (CDK2), cyclin-dependent kinase 4 (CDK4), and cyclin D1 (CCND1)." (PMID 34359836, 2021).
tumor (continued). "Histopathological analysis of the engrafted tumors revealed that YTHDF1 knockdown induced a remarkable decrease in tumor growth, while YTHDF1 overexpression promoted tumor growth." (PMID 33619246, 2021). "m6A sequencing reveals that loss of METTL3 impairs the YTHDF1-mediated translation of SPRED2, which enhances the activation of NF-kB and STAT3 through the ERK pathway, leading to increased tumour growth and metastasis." (PMID 33654093, 2021). "3-MA treatment reduced the increased tumor formation of Hep3B cells with YTHDF1 overexpression (lower)." (PMID 33619246, 2021). "The relationships between YTHDF1 expression and tumor-infiltrated immune cells were analyzed via the TIMER and GEPIA databases." (PMID 34026603, 2021). "In tumor immunity, deletion of YTHDF1 enhances the tumor antigen cross-presentation ability of DCs and promotes the activation of T cells." (PMID 33777035, 2021). "Silencing of YTHDF1 inhibits tumourigenicity in vitro and tumour growth in vivo by inhibiting the Wnt-β-catenin pathway and its expression induces resistance to chemotherapy." (PMID 33461542, 2021). "YTHDF1 plays an essential role in the tumor microenvironment (TME) and participates in immune regulation." (PMID 34026603, 2021). "YTHDF1 in DCs influences the anti-tumor immune response through impairing DCs’ lysosomal cathepsins." (PMID 34526985, 2021). "There are different pathways by which YTHDF1 escalates tumor aggressiveness, one of which is through influencing DCs to be less efficient in presenting tumor antigens to T cells." (PMID 34526985, 2021). "A study found that neoantigen-dependent tumor-specific immunity is considerably controlled by YTHDF1." (PMID 34248650, 2021). "The correlations between YTHDF1 expression and immune checkpoints (ICP), tumor mutational burden (TMB), microsatellite instability (MSI), and neoantigens in human cancers were analyzed via the SangerBox database." (PMID 34026603, 2021). "YTHDF1/YTHDF3 promotes the tumor growth and progression by recognizing m6A-modified integrin subunit alpha 6 (ITGA6) mRNA and promoting its translation." (PMID 33928028, 2021). "FTO depletion and YTHDF1-dependent upregulation of c-Myc promoted tumor cell glycolysis, growth, migration, and invasion and accelerated tumor growth in mice and tumor metastasis to the lung." (PMID 33966037, 2021). "Further, we explored the correlation among the YTHDF1 level, activated tumor-infiltrating lymphocytes, and related biological processes in HCC using immunohistochemistry (IHC), immunofluorescence, and comprehensive bioinformatics analysis." (PMID 34277630, 2021). "Recent studies have revealed m6A methylation components can act as tumor-associated factors, including “writers” (METTL3/14, WTAP and KIAA1429), “erasers” (FTO and ALKBH5), and “readers” (YTHDF1/2/3, HNRNPA2B1, BCDIN3D)." (PMID 33791305, 2021). "As such, compared to WT, a direct reader of m6A, Ythdf1 KO mice showed better cross-presentation of tumor antigens in DC and better cross-priming with CD8+ T cells, leading to high Ag-specific CD8+ T cells in response to tumors." (PMID 33535484, 2021). "We found that the tumor weight and volume in the YTHDF1 knockdown group were significantly lower than those in the control group." (PMID 34088349, 2021). "In accordance with our results, METTL3, YTHDF2, and YTHDF1 were found to be considerably overexpressed between tumor and normal adjacent tissues." (PMID 34248650, 2021). "Mechanistically, m6A-binding protein YTHDF1 can elevate the translation of lysosomal cathepsins in DCs, which consequently degrade the tumor antigens and suppress their antigen-presentation as well as CD8+ T cells-priming ability." (PMID 33746967, 2021). "By recording the tumor growth curve and the weight at the time of sacrifice, we found that the average volume and weight of the tumors in the YTHDF1 knockdown group were markedly reduced compared with the control group." (PMID 33816306, 2021).
tumor (continued). "It appeared that IGF2BP1/3, ELAVL1, HNRNPA2B1, HNRNPC, KIAA1429, RBM15, LRPPRC, FMR1, YTHDF1/2 are highly expressed in the tumor while FTO, METTL14/16, WTAP, YTHDC1 and ZC3H13 are down-regulated." (PMID 35095993, 2021). "Upregulated YTHDF1 mediates m6A modification, playing a critical role in suppressing anti-tumor immune responses." (PMID 34277630, 2021). "To explore the role of YTHDF1 in the immune mechanism and immune response of the tumor microenvironment (TME), we analyzed the correlations between YTHDF1 expression and TMB, MSI, and neoantigens." (PMID 34026603, 2021). "The deletion of YTHDF1 in classical dendritic cells enhances the cross-presentation of tumor antigens and the cross-priming of CD8+ T cells in vivo." (PMID 35087835, 2021). "Loss of YTHDF1 then promotes infiltration of neo-antigen-specific CD8+ T cells and enhances the cross-presentation of tumor antigens to inhibit tumors growth." (PMID 34105069, 2021). "Taken together, these results indicated that the expression of YTHDF1 was significantly up-regulated in HCC and was associated with tumor grade." (PMID 34088349, 2021). "HNRNPC and YTHDF1 were significantly upregulated in tumor tissues compared with corresponding normal tissues, while ZC3H13, YTHDC2 and METTL14 notably decreased." (PMID 34395102, 2021). "Downregulation of YTHDF1 results in the reduction of antigen cross-presentation and alleviation of the cytotoxic lymphocyte response against tumor antigens in dendritic cells, thereby enhancing the effectiveness of the PD-1 blockade therapy." (PMID 34094986, 2021). "In contrast, YTHDF1 acts as a tumour suppressor in melanoma where it promotes the translation of the tumour suppressor HINT2, thus inhibiting tumour development." (PMID 33461542, 2021). "They show that knockdown of YTHDF1 dramatically stunted tumor formation, tumor weights, and volumes in a NSCLC xenograft model." (PMID 34209046, 2021). "In the field of tumor immunotherapy, it was reported that durable neoantigen-specific immunity is suppressed by YTHDF1." (PMID 33795663, 2021). "A previous study reported that YTHDF1 could recognize m6A-marked transcripts encoding lysosomal proteases and result in degradation of neoantigens in dendritic cells, thereby suppressing cross-presentation of tumor neoantigens and cross-priming of CD8+ T cells." (PMID 33500720, 2021). "Clinicopathological analysis demonstrated that YTHDF1 expression was closely correlated with tumor size, microvascular invasion, tumor-node-metastasis, and Edmonson stages." (PMID 33619246, 2021). "Tumor growth was remarkably suppressed in the YTHDF1-KO#1 group, while the opposite phenomenon was observed in the LV-YTHDF1 group." (PMID 33619246, 2021). "IHC analysis revealed that YTHDF1 protein levels were gradually increased with increasing grade of tumor species in NSCLC." (PMID 32106857, 2020). "Taken together, these data suggest that YTHDF1 promotes tumor progression and iron metabolism in HPSCC." (PMID 33204330, 2020). "Ectopic expression of TFRC partially restored the viability, colony formation ability and xenograft tumor growth of YTHDF1-knockdown cells." (PMID 33204330, 2020). "In contrast, YTHDF1 promoted malignant behaviors by regulating the translation of tumor-related genes." (PMID 33363211, 2020). "Overexpression of YTHDF1 was correlated with tumor volume, distant metastasis, histological grade, and neoplasm stage." (PMID 33363211, 2020). "We next explored the mechanism whereby YTHDF1 promoted tumor growth and metastasis by regulating YAP expression in NSCLC." (PMID 32106857, 2020).
tumor (continued). "Further, YTHDF2 facilitates YAP mRNA decay via the AGO2 system in normal tissue, while YTHDF1 promoted YAP mRNA translation by interacting with eIF3a in tumor tissue." (PMID 32106857, 2020). "First, we observed that the expressions of YTHDF1 were higher in tumor tissues than in normal tissues." (PMID 32106857, 2020). "Noticeably, among the m6A readers, YTHDF1 had remarkably different expression levels between HNSCC tumor samples and normal control samples." (PMID 33204330, 2020). "Knocking down YTHDF1 dramatically mitigated tumor growth, as reflected by tumor volumes and weights in the xenograft mouse models." (PMID 33204330, 2020). "Especially, FTO (in all of nine tumor types), RBM15 (in seven of nine tumor types), and YTHDF1 (in six of nine tumor types) showed a wide range of inter-group expression differences." (PMID 33585244, 2020). "In summary, we found that YTHDF1 is closely correlated with iron metabolism and tumor progression in HPSCC." (PMID 33204330, 2020). "After analyzing the data from the ONCOMINE, we found that YTHDF1 copy number in CRC tumor were significant higher than that in normal tissue (blood, colon and rectum)." (PMID 31131257, 2019). "The down-regulation of the YTHDF1 gene can inhibit tumour proliferation and sensitivity to the exposure of fluorouracil, oxaliplatin and other anticancer drugs." (PMID 31810483, 2019). "Knockdown of YTHDF1 dramatically retarded tumor formation, tumor weights, and volumes compared to scrambled shRNA-transformed cells." (PMID 31653849, 2019). "We found that the YTHDF1 copy number in tumor tissue were higher than that in adjacent normal tissue." (PMID 31131257, 2019). "The result indicated that, compatible with the TCGA database study, the expression of Ythdf1 was more strongly stained in tumor tissue than in normal tissue." (PMID 29484125, 2018). "A clinicopathological analysis showed that high Ythdf1 expression was related to tumor malignant characteristics, such as depth, lymph node metastasis, distant metastasis, and a poorer cancer stage." (PMID 29484125, 2018). "Stabilized YTHDF1 then binds to m6A-modified c-Myc mRNA and promotes its decay, thereby repressing c-Myc protein synthesis and its-driven glycolytic flux, which ultimately attenuates the anti-tumor T cell immune response." (PMID 41522342, 2026). "YTHDF1 deficiency inhibits lysosomal gene translation, limiting major histocompatibility complex class I (MHC‐I) and antigen lysosomal proteolysis and, thereby, restoring tumor immune surveillance." (PMID 39802639, 2025). "Furthermore, YTHDF1 expression was significantly elevated in CD133+/LGR5+ tumor cells relative to that in CD133-/LGR5- tumor cells." (PMID 41423446, 2025). "In addition to its role in immune checkpoint regulation, YTHDF1 also influences immune cell infiltration within the tumor microenvironment by modulating the translation of genes involved in immune cell recruitment and activity." (PMID 39911396, 2025). "As expected, DDP treatment upon YTHDF1 knockdown significantly reduced tumor cell viability." (PMID 40251202, 2025). "Inhibiting YTHDF1 eliminates YTHDF1‐dependent tumor growth and metastasis." (PMID 39802639, 2025). "Additionally, ALKBH5 can act as a tumor suppressor to impede NSCLC progression by downregulating YTHDF1/2/3-mediated YAP expression and inhibiting miR-107/LATS2-mediated YAP activity." (PMID 40958857, 2025). "Additionally, researchers have reported that IU1, an inhibitor of USP14, can suppress cell growth and mitigate the tumor-promoting effects induced by YTHDF1 in GC cells." (PMID 41312360, 2025). "To investigate whether the inhibitory effect on tumor growth resulting from Ythdf1 depletion is mediated by Ifn‐γ signaling, we utilized an Ifn‐γ‐blocking antibody in this syngeneic model." (PMID 39587835, 2025).